CCR6 (C-C motif chemokine receptor 6)
Description:
Receptor for the C-C type chemokine CCL20. Binds to CCL20 and subsequently transduces a signal by increasing the intracellular calcium ion levels. Although CCL20 is its major ligand it can also act as a receptor for non-chemokine ligands such as beta-defensins. Binds to defensin DEFB1 leading to increase in intracellular calcium ions and cAMP levels. Its binding to DEFB1 is essential for the function of DEFB1 in regulating sperm motility and bactericidal activity. Binds to defensins DEFB4 and DEFB4A/B and mediates their chemotactic effects. The ligand-receptor pair CCL20-CCR6 is responsible for the chemotaxis of dendritic cells (DC), effector/ memory T-cells and B-cells and plays an important role at skin and mucosal surfaces under homeostatic and inflammatory conditions, as well as in pathology, including cancer and various autoimmune diseases. CCR6-mediated signals are essential for immune responses to microbes in the intestinal mucosa and in the modulation of inflammatory responses initiated by tissue insult and trauma. CCR6 is essential for the recruitment of both the pro-inflammatory IL17 producing helper T-cells (Th17) and the regulatory T-cells (Treg) to sites of inflammation. Required for the normal migration of Th17 cells in Peyers-patches and other related tissue sites of the intestine and plays a role in regulating effector T-cell balance and distribution in inflamed intestine. Plays an important role in the coordination of early thymocyte precursor migration events important for normal subsequent thymocyte precursor development, but is not required for the formation of normal thymic natural regulatory T-cells (nTregs). Required for optimal differentiation of DN2 and DN3 thymocyte precursors. Essential for B-cell localization in the subepithelial dome of Peyers-patches and for efficient B-cell isotype switching to IgA in the Peyers-patches. Essential for appropriate anatomical distribution of memory B-cells in the spleen and for the secondary recall response of memory B-cells (By similarity). Positively regulates sperm motility and chemotaxis via its binding to CCL20.
Synonyms: C-C CKR-6; CC-CKR-6; CCR-6; CKR-L3; GPRCY4; CD196; CKRL3; CMKBR6; GPR29; STRL22; GPR-CY4; DRY-6; DCR2; BN-1; DRY6
Tractability: Small molecule: it belongs to a druggable protein family. Antibody: UniProt places it where antibodies can reach, with high confidence; its Gene Ontology location is reachable by antibodies, with high confidence; UniProt predicts a signal peptide or a membrane-spanning region. PROTAC: a small molecule that binds it is known.
Target class: Chemokine receptor; Peptide receptor (family A GPCR); Family A G protein-coupled receptor; CC chemokine receptor; Membrane receptor
Gene: Protein-coding gene on chromosome 6 (167,111,795 to 167,139,141, forward strand). Ensembl gene ENSG00000112486.
Subcellular location: Cell membrane; Cell surface
Pathways (Reactome):
Signal Transduction: Chemokine receptors bind chemokines; G alpha (i) signalling events
Immune System: Beta defensins
Gene Ontology:
Molecular function: C-C chemokine binding; C-C chemokine receptor activity; protein binding; chemokine receptor activity; signaling receptor activity; G protein-coupled receptor activity
Biological process: calcium-mediated signaling; cell chemotaxis; chemotaxis; positive regulation of flagellated sperm motility involved in capacitation; cellular defense response; dendritic cell chemotaxis; DN2 thymocyte differentiation; DN3 thymocyte differentiation; humoral immune response; immune response; isotype switching to IgA isotypes; leukocyte migration involved in inflammatory response; lymphocyte migration; positive regulation of cytosolic calcium ion concentration; positive regulation of dendritic cell chemotaxis; regulation of T cell migration; signal transduction; T cell migration; thymocyte migration; chemokine-mediated signaling pathway; G protein-coupled receptor signaling pathway
Cellular component: cell surface; plasma membrane; sperm flagellum; sperm midpiece; sperm plasma membrane; sperm principal piece; external side of plasma membrane; membrane
Genetic constraint (gnomAD): Loss-of-function variants: 2 observed, 3.83 expected, observed/expected ratio (o/e) 0.52, 90% interval 0.21 to 1.54. That is too few expected variants to judge how well the gene tolerates losing a copy. Missense variants: 322 observed, 486.51 expected, observed/expected ratio (o/e) 0.66, 90% interval 0.6 to 0.73. Synonymous variants: 193 observed, 192.76 expected, observed/expected ratio (o/e) 1, 90% interval 0.89 to 1.13.
Homologues: Orthologues: macaque CCR6 (95% identical), dog CCR6 (81% identical), guinea pig CCR6 (79% identical), pig CCR6 (79% identical), rabbit CCR6 (76% identical), rat Ccr6 (75% identical), mouse Ccr6 (73% identical), tropical clawed frog ccr6 (48% identical), zebrafish ccr6a (41% identical), zebrafish ccr6b (40% identical). Paralogues in human: CCR7 (38% identical), CXCR1 (36% identical), CXCR2 (34% identical), CCR4 (34% identical), CCR9 (33% identical), CXCR6 (32% identical), ACKR2 (31% identical), CXCR3 (31% identical), ACKR4 (31% identical), CCR3 (31% identical), CCR1 (30% identical), CX3CR1 (30% identical), and 11 more.
Diseases named in the same sentence as CCR6 in open-access papers:
CCR6 is named in the same sentence as 267 diseases in open-access papers, as found by Europe PMC text mining. Sharing a sentence is not in itself a finding about the gene and the disease. The quoted sentences say what the papers report.
psoriasis (73 papers, 2011 to 2025). An autoimmune condition characterized by red, well-delineated plaques with silvery scales that are usually on the extensor surfaces and scalp. "Using previously published single-cell RNA sequencing (scRNAseq) data, we show that CCR6+ epidermal γδ T cells express IL-17–associated genes during psoriasis-like inflammation." (PMID 40073267, 2025). "We reveal an association between the Tγδ17 profile observed in CCR6+ epidermal γδ T cells during psoriasis and the upstream transcription factor Myc." (PMID 40073267, 2025). "It is now clear that CCR6+ epidermal γδ T cells contribute to Tγδ17-associated responses in psoriasis and wound healing, challenging previous assumptions that other dermal and infiltrating cell types were the only IL-17 producers." (PMID 40073267, 2025). "–51 CCR6 has been associated with the pathogenesis of experimental autoimmune encephalitis and uveitis, psoriasis, asthma, and several other diseases." (PMID 38165703, 2024). "Upregulation of hBD-2 and CCR6 (along with LL-37) was also reported in psoriasis, highlighting the importance of the implicated CCR6-dependent signaling pathways in the pathomechanism of these dermatoses." (PMID 39744637, 2024). "CCR6+ T cells have previously been linked to several diseases, including inflammatory bowel disease, systemic lupus erythematosus, psoriasis, and psoriatic arthritis." (PMID 37612718, 2023). "Genetic studies have demonstrated the association between C-C motif chemokine receptor 6 gene (CCR6) and susceptibility to various immune-related diseases, such as rheumatoid arthritis, psoriasis, and lupus nephritis." (PMID 33717080, 2021). "Previous studies have shown that CCL20 S64C alleviates the inflammatory response in psoriasis-like models induced by IL-23, and have been associated with reduced accumulation of CCR6+ IL-17-producing γδT cells in the epidermis." (PMID 33732249, 2021). "The interaction between CCL20 and CCR6 is an indispensable pathogenic mechanism of autoimmune disorders, including psoriasis, and it is considered a distinct therapeutic target." (PMID 34361983, 2021). "Epidermal keratinocytes represent a rich source of C-C motif chemokine 20 (CCL20) and recruit CCR6+ interleukin (IL)-17A–producing T cells that are known to be pathogenic for psoriasis." (PMID 31936670, 2020). "In a similar psoriasis model in which the disease is induced by direct intradermal injection of IL-23, nearly identical results were obtained and CCR6+ dermal γδ T cells were again implicated as the source of pathogenic IL-17." (PMID 25649119, 2015). "CCR6+ cells have been implicated in the pathogenesis of experimental autoimmune encephalitis, experimental autoimmune uveitis, psoriasis, asthma, and many other diseases." (PMID 24223818, 2013). "However, it selectively inhibits the psoriasis-associated pathogenic factor IL-17 and chemokine receptor CCR6 in differentiated Th17 cells through the c-Jun N-terminal kinase (JNK) pathway transcription in differentiated Th17 cells." (PMID 38596682, 2024). "However, CCR6 is implicated in the recruitment of γδT17 cells to inflammatory lesions in several scenarios, such as psoriasis, liver inflammation, and corneal damage, suggesting that modulation of its expression is context specific." (PMID 29731754, 2018). "Our results suggest that CCR6-expressing epidermal γδ T cells in psoriasis exhibit a skewed IL-17–focused response." (PMID 40073267, 2025). "IPA core analysis was performed to further elucidate the biological processes and molecular mechanisms that differentiate CCR6+ epidermal γδ T cell subsets in psoriasis." (PMID 40073267, 2025). "In murine models of wound repair and psoriasis, these epidermal γδ T cells upregulate CCR6 and produce IL-17, with obesity amplifying this response during wound repair but having less effect during psoriasis." (PMID 40073267, 2025). "Previous studies showed that CCR6+ dermal Vγ4 T cells secrete IL-17A in response to skin damage and during psoriasis." (PMID 40073267, 2025).
psoriasis (continued). "To validate the scRNAseq findings that CCR6+ epidermal γδ T cells produce IL-17A during psoriasis, we examined IL-17A production in vivo using IL-17A GFP reporter mice." (PMID 40073267, 2025). "The majority of murine dermal Vγ4 and Vγ6 T cells express CCR6, which facilitates recruitment to the epidermis in response to psoriasis-like inflammation." (PMID 40073267, 2025). "We validate these findings in murine models of wound repair and imiquimod (IMQ)-induced psoriasis-like inflammation where CCR6 and/or IL17A are expressed by epidermal γδ T cells in vivo." (PMID 40073267, 2025). "Although several chemokines, such as CCL13, CXCL12, CXCL10, CCL27, and CCR6, have been identified in the context of psoriasis, CXCL10, in particular, has been suggested as a biomarker for psoriasis progression." (PMID 38829444, 2024). "DEFB4A has been shown to mediate the activation of CCR6 Th17 cells, further supporting its role in psoriasis." (PMID 38596682, 2024). "The deletion of CCR6 in mice has been shown to impede the development of a psoriasis-like phenotype following IL-23 injection." (PMID 38829444, 2024). "Signaling via the CCL20/CCR6 axis was shown to be more pronounced in the lesional skin of human psoriasis and in mouse models of psoriasis-like skin inflammation." (PMID 37049538, 2023). "Considerable attention has been given to CCR6 in the pathology of several autoimmune diseases, including psoriasis, multiple sclerosis (MS), vitiligo, rheumatoid arthritis (RA) and atopic dermatitis (AD)." (PMID 37092451, 2023). "This engineered dimer was able to bind and to activate CCR6 but inhibited T cell-mediated chemotaxis, resulting in a reduction in inflammation in an IL-23-induced mouse model of psoriasis." (PMID 37049538, 2023). "The role of CCR4, CCR8, CCR10, and CCR6 or their ligands has been proposed in atopic dermatitis (AD), psoriasis, cutaneous lupus erythematosus, systemic sclerosis, or malignant skin tumors, but not in CU." (PMID 37371632, 2023). "One of the strengths of our study is that we included a sufficient amount of 45 psoriasis and PsA patients and 17 healthy controls, all sex and age-matched, to provide insight in the distribution of CCR6+ Th subpopulations among psoriasis and PsA patients." (PMID 35045868, 2022). "This demonstrates that CCL20, together with its receptor, CCR6, are potential targets for the treatment of psoriasis." (PMID 33732249, 2021). "For instance, CCR6 is highly expressed by CD8 TRM in psoriasis lesions, and CCR6+ CD8 TRM precursors possibly enter the skin according to the concentration gradient of the ligand CCL20 that is upregulated in psoriatic keratinocytes." (PMID 34884736, 2021). "CCR6 antagonist would be a potential treatment for inflammatory diseases such as psoriasis or rheumatoid arthritis." (PMID 34225700, 2021). "The chemokine receptor CCR6 is a marker for T cells secreting IL-17 and IL-22, which are the key cytokines in psoriasis pathogenesis." (PMID 32139717, 2020). "We established a psoriatic HSC (pHSC) by incorporating polarized Th1/Th17 cells or CCR6+CLA+ T cells derived from psoriasis patients into the constructs." (PMID 32139717, 2020). "CCR6-expressing cells are thought to play a major role in a number of Th17-mediated autoimmune diseases including T1D, psoriasis and RA and targeting these cells or the cytokines they produce is an area of active clinical trial activity." (PMID 31749806, 2019). "In a murine model of IMQ-induced psoriasis, IL-23 was reported to induce γδ T17 cells in dLNs, which are the major IL-17 producers and express the chemokine receptor CCR6 (CCR6+ γδ T17 cells)." (PMID 31705000, 2019). "The percentage of CCR6+CXCR3− cells within the CD4+ TEM subset in the total cohort of psoriasis and PsA patients significantly correlated with serum concentration of CRP." (PMID 31350460, 2019).
psoriasis (continued). "CCR6 inhibition by a hitherto unidentified small molecule inhibitor named CCX9664 was published by a team of researchers experimenting with psoriasis." (PMID 30453514, 2018). "Recently, blocking CCR6 was tested in a murine model of psoriasis and resulted in a reduced recruitment of Th17 cells to the plaque and reduced plaque thickness." (PMID 30347808, 2018). "It was identified as a highly potent molecule on both human and mouse CCR6 that is suitable for use in the treatment of diseases, rheumatoid arthritis, psoriasis, and multiple sclerosis (MS)." (PMID 30453514, 2018). "CCR6 is, therefore, being investigated as a possible new target in the treatment of both psoriasis and PsA." (PMID 30109481, 2018). "CCR6+ cells also migrate to the epidermis or dermal-epidermal junction in response to psoriasis-triggering stimuli in murine models of psoriasis." (PMID 30109481, 2018). "Taken together, these data suggest that ERDR1 regulates Th17 cell migration towards psoriatic lesional skin through the inhibition of the CCL20/CCR6 axis, resulting in the attenuation of psoriasis-like skin inflammation." (PMID 26901187, 2016). "The recruitment of leukocytes to the skin is a critical component of psoriasis, and published data suggest that the chemokine receptor CCR6 is an important contributor to this process." (PMID 27982014, 2016). "Production of IL-23 by Langerhans cells has in fact now been shown to be required for the development of psoriasis in Imiquimod-treated mice, and for inducing IL-17 production from CCR6+ γδ T cells." (PMID 25649119, 2015). "Increased CCL20 expression in keratinocytes of patients with psoriasis has been reported, and the contribution of CCR6-positive Th17 cells to the pathology of inflammatory diseases has been suggested clinically." (PMID 25172034, 2014). "In IL-23 induced psoriasis, CCR6+Th17+ cells accumulate in psoriatic skin where CCL20 (the CCR6 ligand) expression is abundant." (PMID 22229105, 2012). "There is abundant CCL20 protein staining in psoriasis, which is chemotactic for CCR6+ immature DCs and Th17 cells." (PMID 22348003, 2012). "In psoriasis, CCL20 produced at sites of skin inflammation is a chemoattractant for skin-homing cutaneous lymphocyte-associated antigen (CLA)+CCR6+ T cells and Th17 cells in the circulation." (PMID 21311769, 2011). "CCR6 has been associated with numerous diseases including psoriasis and is a target for therapeutic intervention, but CCR6 targeting drugs have not yet been approved by the Food and Drug Administration." (PMID 40073267, 2025). "CCL20, in particular, plays a pivotal role in psoriasis by binding to its receptor CCR6." (PMID 38605947, 2024). "CCR6+ T lymphcytes are involved in an imiquimod-induced psoriasis model." (PMID 37218898, 2023). "In addition, CCR8 and CCR6 were described for their role in atopic skin diseases and psoriasis, respectively." (PMID 37371632, 2023). "In particular the CCR6+ memory Th cells are of interest for psoriasis and PsA." (PMID 35045868, 2022). "In our study, the levels and functional capacity of peripheral pro-inflammatory Th1, Th17, and additional CCR6+T cell sub-gated populations from psoriasis patients that were treated with anti-IL-17 or anti-IL-17R targeted biologic therapy were explored for the first time." (PMID 35925616, 2022). "CCL20 plays an important role in psoriasis by recruiting CCR6+Th17 cells into the lesional skin." (PMID 36035154, 2022). "This suggests the potential relevance of CCR6/CCL20 as a therapeutic target for psoriasis." (PMID 33732249, 2021). "Taken together, CCR4 and CCR6 are important for the pathogenesis of psoriasis." (PMID 34831296, 2021). "In both IL-23- and IMQ-induced psoriasis animal models, dermal γδT-cells mainly infiltrate the dermis and then migrate to the epidermis, which is associated with IL-17 expression levels in psoriatic lesions and highly dependent on the CCL20/CCR6 axis." (PMID 32355189, 2020).